CPHXL2 (cytoplasmic polyadenylated homeobox like 2)
Gene: Protein-coding gene on chromosome 16 (75,660,227 to 75,677,009, reverse strand). Ensembl gene ENSG00000284484.
Subcellular location: Nucleus
Gene Ontology:
Molecular function: DNA-binding transcription factor activity, RNA polymerase II-specific; RNA polymerase II cis-regulatory region sequence-specific DNA binding; DNA binding
Biological process: regulation of transcription by RNA polymerase II
Cellular component: nucleus
Homologues: Orthologues: chimpanzee CPHXL2 (98% identical), mouse Cphx1 (16% identical), rat Cphx1 (14% identical), Drosophila melanogaster en (8% identical), Drosophila melanogaster inv (8% identical), Caenorhabditis elegans ceh-16 (6% identical). Paralogues in human: CPHXL (79% identical), EN1 (8% identical), EN2 (8% identical).